PPARG (peroxisome proliferator activated receptor gamma)
Diseases named in the same sentence as PPARG in open-access papers (continued):
Sharing a sentence is not in itself a finding about the gene and the disease.
type 2 diabetes (continued). "PPARγ agonists have been widely used for the treatment of type II diabetes; however, they are also known to exhibit anti-inflammatory and anti-oxidant properties in several models of CNS disorders." (PMID 28886715, 2017). "A new dual PPARα and PPARγ agonist known as Saroglitazar, with a higher activity for PPARα and moderate PPARγ activity, has been approved for the treatment of type 2 diabetes in India in order to control diabetic dyslipidemia." (PMID 28243251, 2017). "This study provides an important insight of future translational and clinical research into targeting PPARγ regulation of lipid metabolism in lung cancer patients accompanying type 2 diabetes." (PMID 29137280, 2017). "Thiazolidinediones (TZDs) are synthetic ligands (potent activators of PPARγ) that have been used in treating type 2 diabetes but were finally withdrawn due to critical cardiovascular diseases and bladder cancers as side effects." (PMID 29225614, 2017). "Due to participation of PPARγ in lipid and glucose metabolism, it is a target for the PPARγ agonists which are used in the treatment of type 2 diabetes." (PMID 28656106, 2017). "The most widely studied therapeutic use of PPARγ has been in the treatment of insulin resistance and type II diabetes." (PMID 28570659, 2017). "Thiazolidinediones (TZDs) are PPARγ agonists and orally effective medicines for metabolic syndrome and type 2 diabetes." (PMID 29163813, 2017). "TZDs, such as pioglitazone and rosiglitazone, are synthetic ligands of peroxisome proliferator-activated receptors gamma (PPARγ) used in therapeutic treatments for patients diagnosed with type II diabetes mellitus." (PMID 28348577, 2017). "The PPARγ agonists rosiglitazone and pioglitazone were routinely prescribed for the treatment of type II diabetes during the early to mid-2000s." (PMID 29181019, 2017). "In particular, dual PPARα and PPARγ agonists have been accepted to be promising for the treatment of type 2 diabetes with dyslipidemia." (PMID 28042289, 2016). "The thiazolidinediones (TZDs) or glitazones (e.g., rosiglitazone and pioglitazone) are considered as specific ligands for PPARγ and are being used for treating hyperglycemia in patients with type 2 diabetes." (PMID 27708429, 2016). "Drugs called thiazolidinediones (or TZDs for short), which are normally used to treat type 2 diabetes, activate PPARγ and therefore have anti-tumor effects." (PMID 27692066, 2016). "Thiazolidinediones (TZDs or glitazones) are ligands of the nuclear receptor transcription factor peroxisome proliferator-activated receptor gamma (PPAR gamma) that have recently been developed as insulin sensitizers to treat patients with type 2 diabetes." (PMID 26770984, 2016). "In the present study we investigated the effect of Pioglitazone (Pio), a PPARγ agonist commonly used in clinic for the treatment of type II diabetes mellitus, on six GSC lines isolated from GBM." (PMID 27313600, 2016). "Recent studies have reported that synthetic PPARγ agonists, already in clinical use for the treatment of type II diabetes, exhibit antineoplastic effects in a wide range of malignant tumor cells, including glioma cells." (PMID 27313600, 2016). "Thiazolidinedione drugs, such as RGZ or pioglitazone, agonists of PPARγ, are used to treat type 2 diabetes by improving insulin sensitivity." (PMID 28066247, 2016). "Rosiglitazone (BRL), a PPARγ agonist used in type 2 diabetes treatment, has been shown to inhibit CXCR4 expression and to reduce the malignancy in colon, lung and prostate cancer cells." (PMID 27556298, 2016). "The thiazolidinedione rosiglitazone, a peroxisome proliferator activated receptor gamma (PPARγ) agonist, is an insulin sensitizing agent that improves glycaemic control and a variety of other metabolic disturbances in patients with type 2 diabetes." (PMID 26734075, 2016).
type 2 diabetes (continued). "The purpose of this study was to investigate the underlying mechanisms by which aging affects adipose tissue remodeling in a type 2 diabetic animal model and through which PPARγ activation modulates aging-related fat tissue distribution." (PMID 26894429, 2016). "Recently, we provided evidence that Pio improved retinal insulin signaling in the BBZDR/Wor type 2 diabetes rat model in a PPARγ-dependent manner." (PMID 26336514, 2015). "PPARγ is a target for pharmaceutical intervention in type 2 diabetes, and insight into interactions between PPARγ, RXRα, and DNA is of interest in understanding the function and regulation of this complex." (PMID 25954810, 2015). "Novel selective PPARγ ligands with partial agonist-binding properties would be advantageous as not only candidates for the treatment of type 2 diabetes but also chemical probes for elucidation of the biological function of PPARγ." (PMID 25827822, 2015). "For example, several GWAS loci for type 2 diabetes contain genes known to harbour causal coding variants for rare Mendelian syndromes related to type 2 diabetes (e.g. HNF1A, HNF1B, WFS1, PPARG, KCNJ11, HNF4A, GCK)." (PMID 26702037, 2015). "Pioglitazone (PIO) is a peroxisome proliferator-activated receptor-γ (PPARγ) agonist in clinical use for treatment of type 2 diabetes (T2DM)." (PMID 25671601, 2015). "Thiazolidinediones (TZD) is a PPARγ agonist that possesses high binding affinity to PPARγ and has been used commercially to treat type 2 diabetes." (PMID 26703529, 2015). "Thiazolidinedione (TZD) encompasses a class of drugs that activate peroxisome proliferator activated receptor gamma (PPARγ), which is a key transcription factor that induces insulin-sensitive genes and is targeted in Type II diabetes mellitus treatment." (PMID 25807446, 2015). "Thiazolidinediones (TZDs) are synthetic peroxisome proliferator-activated receptor-γ (PPARγ) agonists that have been widely used in treating type 2 diabetes and can inhibit cellular growth through PPARγ-dependent or -independent pathways." (PMID 25742642, 2015). "To date, the nuclear receptor PPARβ/δ has been less studied than PPARα and PPARγ, which are drug targets for the treatment of dyslipidemia and type 2 diabetes, respectively." (PMID 24203162, 2014). "Treatment with TZDs activates PPARγ pathway reducing insulin resistance and blood glucose levels in patients with diabetes type 2." (PMID 25246934, 2014). "A score of 6 is strong evidence for the involvement of PPARγ, and because we already know its importance in type 2 diabetes therapy, this example serves to validate DiCE." (PMID 25071867, 2014). "Agonists of PPARγ rosiglitazone and pioglitazone have been widely used for many years for treating type 2 diabetes, owing to their effectiveness in promoting insulin sensitivity." (PMID 24693278, 2014). "Clinical importance of PPARγ has risen especially after the use of TZDs drugs for the treatment of diabetes mellitus type 2." (PMID 25246934, 2014). "Thiazolidinediones (TZD) are high affinity synthetic agonists for PPARγ that improve glycemic control in type 2 diabetes, and have been reported to improve vascular function and to lower arterial pressure." (PMID 25122005, 2014). "Thiazolidinediones (TZDs) are synthetic peroxisome proliferator-activated receptor gamma (PPARγ) agonists, currently used in the treatment of type 2 diabetes as hypoglycaemic agents." (PMID 23533381, 2013). "PPARg-agonists are used to treat type 2 diabetes by redistributing adipose tissue from abdominal visceral to subcutaneous compartment, which is thought to be preferable and improve insulin sensitivity." (PMID 23754948, 2013). "Given the beneficial effects of PPARγ agonists in type 2 diabetes, their molecular mechanisms of decreasing blood glucose have been widely studied." (PMID 23424659, 2013).
type 2 diabetes (continued). "Approved for the treatment of type 2 diabetes, PPARγ agonists can improve glucose disorders mainly through insulin-sensitizing effects in muscle and adipose tissue." (PMID 23424659, 2013). "TCF7L2 rs7903146, KCNJ11 rs5219, PPARγ rs1801282 and CAPN10 rs3842570, rs3792267, and rs5030952 were typed and associations with type 2 diabetes and phenotypic traits examined." (PMID 24059590, 2013). "Two further classic type 2 diabetes risk alleles, KCNJ11 rs5219 (G) (influencing insulin secretion) and PPARγ rs1801282 (C) (influencing insulin sensitivity) are considered to be very rare and very frequent, respectively, in individuals of African descent." (PMID 24059590, 2013). "PPARγ agonists including rosiglitazone and piglitazone are very effective agents in treatment of type-2 diabetes." (PMID 24489534, 2013). "PPARγ upregulation has been reported to improve metabolic indices in type 2 diabetes and other chronic conditions, while its downregulation has been shown to confer antiobesity effects." (PMID 23389305, 2013). "The protective allele of PPARγ rs1801282 and the risk-conferring allele of KCNJ11 rs5219 are nearly absent and thus have a debatable relevance for population-wide variation in type 2 diabetes risk in this area." (PMID 24059590, 2013). "Specifically, Rb1 and Rg1 treatment improved PPARγ expression and decreased total cholesterol, triglyceride, and glucose levels in peripheral blood of patients with type 2 diabetes." (PMID 23520555, 2013). "PPARγ agonists including Rosi and piglitazone are potent agents in treatment of type-2 diabetes mainly via sensitizing the insulin signaling." (PMID 24489534, 2013). "PPARγ is the pharmacological target of the insulin-sensitizing thiazolidinediones (TZDs) that have been widely used in the treatment of type 2 diabetes." (PMID 24454336, 2013). "Full PPARγ agonists, such as the thiazolidinediones (TZDs), have been widely used to treat type 2 diabetes." (PMID 24454336, 2013). "The seven loci shed new light on regions containing genes with a reported role for type 2 diabetes (PPARG, ADAMTS9, VEGFA), lipids (GRB14, MAP3K1) and hormone metabolism (HSD17B4)." (PMID 23754948, 2013). "PPARγ agonists have been used effectively to treat type 2 diabetes which act in part to promote proper storage of fat into lipid droplets." (PMID 24130751, 2013). "PPARγ agonists have been proven to be potent insulin sensitizing agents for treating type II diabetes, but induce body weight gain in patients." (PMID 23049539, 2012). "This insulin sensitizing activity affords the therapeutic potential of PPARγ activation in management of hyperglycemia and insulin resistance in type 2 diabetes." (PMID 22899986, 2012). "Pioglitazone is an activator of peroxisome proliferator-activated receptor gamma that has been used to treat Type 2 Diabetes, and in this context, was correlated with a decreased incidence of breast cancer." (PMID 23144783, 2012). "Synthetic PPARγ agonists, the thiazolidinediones (TZDs), are used in type II diabetes therapy as insulin sensitizers to overcome insulin resistance in target tissues." (PMID 23213321, 2012). "The insulin sensitizing thiazolinediones, which are selective ligands of the nuclear transcription factor PPARγ, were the first drugs used to treat insulin resistance in patients with type II diabetes." (PMID 22936949, 2012). "PPARγ is a key regulator of energy metabolism and is best known for serving as a therapeutic target for management of type 2 diabetes." (PMID 22899986, 2012). "PPARγ, expressed in adipose tissue and liver, regulates lipid storage and glucose metabolism and is the target of type 2 diabetes drugs, thiazolidinediones (TZDs)." (PMID 22792089, 2012). "In recent years, peroxisome proliferator-activated receptor gamma (PPARγ) has been reported to be a target for the treatment of type II diabetes." (PMID 22693486, 2012).
type 2 diabetes (continued). "The PPAR receptors have 3 identified subtypes: PPARα, PPARβ and PPARγ, all of which have been treated as attractive targets for developing drugs to treat type 2 diabetes." (PMID 23119024, 2012). "SPPARMs are PPARγ modulators that exhibit potent insulin sensitization activity but are antiadipogenic in animal models of type II diabetes." (PMID 23213321, 2012). "The ability of PPARα and PPARγ agonists to induce neoangiogenesis therefore has important implications for the clinical and therapeutic management of type II diabetes." (PMID 23213321, 2012). "These drugs are high affinity ligands of PPARγ with insulin sensitizing effects and used in the treatment of type 2 diabetes." (PMID 22792089, 2012). "A current pharmacological approach to counteract insulin resistance and type 2 diabetes is the use of thiazolidinediones (TZDs), which are agonists on peroxisome proliferator-activated receptor γ (PPARγ)." (PMID 23102228, 2012). "PPARγ agonists improve insulin sensitivity and induce glycaemic control in diabetic animals as well as in patients with type 2 diabetes." (PMID 23226761, 2012). "Targeting of WAT by thiazolidinediones (TZDs), activators of peroxisome proliferator-activated receptor γ (PPARγ) a ‘master’ regulator of fat cell biology, is a current therapy for the treatment of type 2 diabetes." (PMID 23102228, 2012). "Not only was PPARγ found to be an important regulator of adipose function, lipogenesis and lipid storage, it was also demonstrated that the TZD class of drugs, which can be used for the treatment of type 2 diabetes, are cognate ligands of PPARγ." (PMID 21382489, 2011). "One region, upstream of the gene FAM78B, contains three binding sites for the transcription factor PPARG and two binding sites for HNF1A, both previously implicated in the pathology of type 2 diabetes." (PMID 22216000, 2011). "The insulin-sensitizing properties of thiazolidinediones (TZDs), a family of PPARγ agonist compounds used to treat type 2 diabetes, have been traditionally attributed to their ability to enhance adipogenesis, via activation of PPARγ." (PMID 22087241, 2011). "All three patients had type 2 diabetes mellitus and hypertension, suggesting the important role of PPARγ in regulation of insulin sensitivity, glucose homeostasis and blood pressure." (PMID 21382489, 2011). "PPARγ agonists, such as the glitazones, used for the treatment of type 2 diabetes (T2D), reduce either adipocyte 2-AG concentrations or CB1 receptor expression levels, or both." (PMID 20426869, 2010). "In peripheral tissue, correlations have been observed between the BMI of the tissue donors and mRNA expression of type 2 diabetes susceptibility genes including FTO, PPARG and TCF7L2." (PMID 20548773, 2010). "Peroxisome proliferator activated receptor γ (PPARγ) agonists are widely used in the treatment of type 2 diabetes." (PMID 20069049, 2010). "Two PPARγ agonists, rosiglitazone and pioglitazone, are currently approved for the systemic treatment of type II diabetes." (PMID 20617179, 2010). "Rosiglitazone (RGZ), a PPARγ agonist used in type 2 diabetes treatment, has been shown to reduce the malignancy in variety of cancers." (PMID 20226009, 2010). "PPARγ agonists, also called thiazolidinediones (TZDs), are widely used as insulin-sensitizing agents in the treatment of type 2 diabetes." (PMID 20069049, 2010). "A range of complementary metabolic profiling approaches were used to study key tissues involved in type 2 diabetes from ob/ob mice treated with a PPARδ or a PPARγ agonist to understand the role of PPAR-δ in regulating systemic metabolism." (PMID 19968882, 2009). "Activation of PPARG with thiazolidinediones is used to stimulate insulin sensitivity in the treatment of type 2 diabetes." (PMID 20016803, 2009). "PPARγ activation in type 2 diabetic patients results in a marked improvement in insulin and glucose parameters, resulting from an improvement of whole-body insulin sensitivity." (PMID 20182551, 2009).
type 2 diabetes (continued). "We confirmed the effects of SNPs from PPARG, KCNJ11, CDKAL1, CDKN2A-CDKN2B, IDE-KIF11-HHEX, IGF2BP2 and SLC30A8 on risk for type 2 diabetes, with odds ratios ranging from 1.114 to 1.406 (P value range from 0.0335 to 1.37E-12)." (PMID 19862325, 2009). "Because PPARγ activation by thiazolidinedione increased insulin sensitivity in type 2 diabetes, understanding the long term impact of PPARγ activation on steroid sex hormones in males is critical." (PMID 19536350, 2009). "The current study confirmed the association between PPARG, KCNJ11, CDKAL1, CDKN2A-CDKN2B, IDE-KIF11-HHEX, IGF2BP2 and SLC30A8 and type 2 diabetes." (PMID 19862325, 2009). "In conclusion, we confirmed the association between PPARG, KCNJ11, CDKAL1, CDKN2A-CDKN2B, IDE-KIF11-HHEX, IGF2BP2, SLC30A8 variants and type 2 diabetes." (PMID 19862325, 2009). "Among the important PPARγ synthetic activators are the thiazolidinediones (TZDs) drugs often used in the treatment of type 2 diabetes." (PMID 19536350, 2009). "Rosiglitazone is a PPAR-γ (peroxisome proliferator-activated receptor-gamma) agonist that has been shown to improve insulin sensitivity, resulting in improved glycaemic control in people with type 2 diabetes." (PMID 18435852, 2008). "Thiazolidinediones (TZDs) are peroxisome proliferator-activated receptor subtype γ (PPARγ) activators that are clinically used as an insulin sensitizer for glycemic control in patients with type 2 diabetes." (PMID 18784848, 2008). "PPARγ is involved in glucose metabolism throughthe improvement of insulin sensitivity and represents a potential therapeutictarget of type 2 diabetes." (PMID 18584037, 2008). "Rosiglitazone (RGZ), a synthetic ligand of PPARγ used in the treatment of Type 2 diabetes, inhibits growth of some tumor cells and is involved in other processes related to cancer progression." (PMID 18261208, 2008). "PPARγ2 is expressedexclusively in adipose tissue and plays a pivotal role in adipocyte differentiation.PPARγ is involved in glucose metabolism through the improvement of insulin sensitivityand represents a potential therapeutic target of type 2 diabetes." (PMID 18584037, 2008). "It is this latter activity that hasled to the development of specific PPARγ agonistsfor the treatment of type II diabetes." (PMID 18645613, 2008). "The TZD pioglitazone (Actos) is an FDA-approved PPARγ agonist used to treat type 2 diabetes, with a good safety profile, currently being tested in clinical trials of other neurological diseases including AD and MS." (PMID 17207275, 2007). "The thiazolidinediones, which selectively activate PPARγ, are hypoglycaemic molecules that are used to treat type II diabetes." (PMID 16197558, 2005). "Additionally, 4 genes (APOB, INSR, PPARG, APOC3) had prior genetic associations with MASLD while another 12 genes had associations with a MASLD-related phenotype (type 2 diabetes, BMI-adjusted waist-to-hip ratio (WHRadjBMI), metabolic syndrome)." (PMID 40065360, 2025). "While PPARγ agonists are known to enhance insulin sensitivity and aid in managing type 2 diabetes, their clinical use is often restricted due to significant side effects, including an increased risk of heart failure, weight gain, bone fragility, edema, and cancer." (PMID 40286240, 2025). "Therefore, given its ability to enhance insulin sensitivity and improve glucose uptake, PPARγ is a major therapeutic target for treating type 2 diabetes." (PMID 40286240, 2025). "PPARγ agonists are well-known regulators of glucose and lipid metabolism, with established clinical applications in treating metabolic disorders such as type 2 diabetes, dyslipidemia, and non-alcoholic fatty liver disease." (PMID 39911401, 2025). "Pioglitazone, a PPARγ agonist used in type 2 diabetes, exhibits anti-inflammatory properties." (PMID 41035823, 2025). "Clinical trial data for type 2 diabetes showed that PPARγ agonist rosiglitazone could increase the incidence of adverse cardiovascular events." (PMID 38280036, 2024).